GM2A (ganglioside GM2 activator)
Description:
Lipid-binding and transfer protein essential for lysosomal degradation of ganglioside GM2. Extracts single GM2 molecules from intralysosomal luminal vesicle (ILV) membranes and presents them in soluble form to beta-hexosaminidase A (HEXA) for cleavage of N-acetyl-D-galactosamine and conversion to GM3. Forms a stoichiometric GM2-GM2A complex that serves as the substrate for HEXA. Also stimulates the breakdown of glycolipid GA2 by HEXA (By similarity). Possesses dual function: membrane lipid mobilization/solubilization and lipid substrate presentation to hydrolases. The large binding pocket can accommodate several single-chain phospholipids and fatty acids (By similarity). Exhibits some calcium-independent phospholipase activity (By similarity). Participates in cholesterol transfer.
Synonyms: SAP-3; GM2-AP; GM2AP
Tractability: Small molecule: a structure with a bound ligand is known; it has a high-quality binding pocket. Antibody: its Gene Ontology location is reachable by antibodies, with high confidence; UniProt predicts a signal peptide or a membrane-spanning region. PROTAC: ubiquitination databases record sites on it; its protein half-life has been measured.
Gene: Protein-coding gene on chromosome 5 (151,212,150 to 151,270,440, forward strand). Ensembl gene ENSG00000196743.
Subcellular location: Lysosome
Subcellular location (Human Protein Atlas): Cytosol; Vesicles
Pathways (Reactome):
Immune System: Neutrophil degranulation
Metabolism: Glycosphingolipid catabolism
Gene Ontology:
Molecular function: protein binding; lipid transporter activity; sphingolipid activator protein activity; beta-N-acetylgalactosaminidase activity; beta-N-acetylhexosaminidase activity; enzyme activator activity; phospholipase activator activity
Biological process: ganglioside catabolic process; glycosphingolipid catabolic process; lipid transport; ganglioside metabolic process
Cellular component: extracellular exosome; azurophil granule lumen; cytoplasmic side of plasma membrane; extracellular region; lysosomal lumen; apical plasma membrane; basolateral plasma membrane; lysosome
Genetic constraint (gnomAD): Loss-of-function variants: 6 observed, 12.23 expected, observed/expected ratio (o/e) 0.49, 90% interval 0.27 to 0.97. The upper end of that interval is the gene's LOEUF score, 0.97, which puts it in group 4 of 6, group 1 being the genes least tolerant of losing a copy. Missense variants: 246 observed, 254.27 expected, observed/expected ratio (o/e) 0.97, 90% interval 0.87 to 1.08. Synonymous variants: 101 observed, 101.1 expected, observed/expected ratio (o/e) 1, 90% interval 0.85 to 1.18.
Gene-disease validity (ClinGen):
ClinGen rates the evidence that GM2A causes each of these diseases.
Tay-Sachs disease AB variant (autosomal recessive): Definitive.
Homologues: Orthologues: chimpanzee GM2A (88% identical), macaque GM2A (82% identical), mouse Gm2a (68% identical), rat Gm2a (67% identical), pig GM2A (64% identical), guinea pig GM2A (62% identical), dog GM2A (58% identical), zebrafish gm2a (50% identical), tropical clawed frog gm2a (47% identical), zebrafish GM2A (37% identical).